IL6 (interleukin 6)
Diseases named in the same sentence as IL6 in open-access papers (continued):
Sharing a sentence is not in itself a finding about the gene and the disease.
infection (continued). "We determined the expression levels of mRNA encoding the three pro-inflammatory cytokines IL-6, IL-8, and TNFα to help understand the impact that 6K-F17 treatment has on infection-mediated inflammation." (PMID 32092967, 2020). "Many pro-inflammatory cytokines, such as TNF-α and IL-6, reportedly triggered in sepsis, which caused an overwhelming immune response against the infection." (PMID 32625095, 2020). "In contrast, IL-6 deficient C57BL/6 mice were able to control the infection by L. major as the wild type corresponding mice." (PMID 31134162, 2019). "MDM-infection assays using 2:1 or higher MOIs report upregulation of IL-10, IL-6, and tumor growth factor (TGF)-β, cytokines associated with suppression of cell mediated immunity." (PMID 31614819, 2019). "In all patients, serum IL-6 and ferritin were dynamically observed and we found that grade 4–5 infection caused changes that were characteristically different from CRS." (PMID 31640816, 2019). "Simultaneously, as a pro-inflammatory factor, up-regulation of IL-6 transcripts was detected in many fish defending against various pathogenic infections." (PMID 31130962, 2019). "Infection of mice with African trypanosomes (including T. congolense) is associated with high levels of serum proinflammatory cytokines (including IL-12p40, IL-6, and TNF-α) and nitric oxide (NO)." (PMID 31824484, 2019). "A recent study reported that IL-6 level is a diagnostic marker of infection and a prognostic marker, in patients with organ dysfunction." (PMID 31243609, 2019). "Infection and inflammation cause significant upregulation of IL-6, which features pleiotropic activity and mediates various biological functions." (PMID 31523783, 2019). "A recent study reported that the IL-6 level is a diagnostic marker of infection as well as a prognostic marker in patients with organ dysfunction." (PMID 31718563, 2019). "IL-6 is a key cytokine which is strongly upregulated during infection/inflammation and associated with variety of systemic autoimmune diseases." (PMID 31523783, 2019). "Whereas TNFα secretion was increased upon infection independently of pilus expression, pilus-positive gonococci caused an increase in IL-8 and suppression of IL-6 secretion." (PMID 31417529, 2019). "Interleukin-6 (IL-6) is an immune molecule associated with acute inflammation, particularly in response to recent infection or injury." (PMID 31802241, 2019). "For example, in the patients with organ dysfunction in the ICU, serum IL-6 levels had the highest diagnostic value for infection among IL-6, PCT, presepsin, and CRP levels." (PMID 31261907, 2019). "A recent study reported that serum IL-6 levels had the highest diagnostic value for infection in patients with organ dysfunction compared with PCT and CRP levels." (PMID 31718563, 2019). "Second, the synergistic interaction between IL-6 and interleukin 17 (IL-17) have been associated with viral persistence and exacerbated clinical outcome during infection with Theiler's murine encephalomyelitis virus (TMEV)." (PMID 31134045, 2019). "Infection activates endothelial cells and causes significant increase in secreted protein levels of inflammatory cytokines IL-6 and IL-8." (PMID 31681283, 2019). "While overexpression of IL6 is associated with various inflammatory conditions, this can be a consequence of infection; whereas innate IL6 deficiency can lead to impaired immunity against microbial infection." (PMID 30795743, 2019). "Binding of IL-6 to the IL-6 receptor mediates intracellular signal transduction pathways, which often serve to boost innate immune responses during pathogenic infections." (PMID 31998294, 2019). "In contrast to IL-6, increased IL-10 expression counteracts T cell responses, enhances injury-associated immunosuppression, and increases susceptibility to infection." (PMID 31152269, 2019).
infection (continued). "Loss-of-function (LOF) mutations affecting GP130 and STAT3 lead to multisystem disorders encompassing IgE elevation, infection susceptibility, and connective tissue abnormalities; however, the specific contribution of IL-6 remains undefined." (PMID 31235509, 2019). "First, higher infection burden was associated with higher levels of IL-6 and CRP, but this association was explained by body mass, atopic disorder and socio-economic status." (PMID 29198208, 2018). "Cytoskeletal rearrangements in epithelial and subepithelial cells are induced by proinflammatory cytokines TNF-α and IL-6, that are known to be up-regulated during infection caused by M. hyopneumoniae." (PMID 30523267, 2018). "Some athletes appear to be susceptible to illness and infection during periods of increased training load, and exercise-induced IL-6 responses are higher in illness-prone athletes compared with healthy athletes (10 fold vs. 5 fold)." (PMID 29910316, 2018). "Body weight loss on days 6–10 post infection, viral titers, and the pro-inflammatory cytokine IL-6 were significantly reduced in the TAT-P1/DIG-3-treated mice when compared with those of mice treated with zanamivir or PBS." (PMID 29907765, 2018). "Symptomatology induced by hMPV-infection is caused by a typical Th17-like immune response, characterized by the secretion of interleukin (IL)-6 and TNF-α in the lungs." (PMID 30405642, 2018). "IL-6 was the only cytokine positively and significantly associated with mortality at time point 2 (6–9 days after infection) (HR 2.03, 95% CI 1.31–3.14, p = 0.002)." (PMID 29695270, 2018). "IL-6 also has a crucial role in protecting against Mtb, as infection with Mtb was observed to be lethal in IL-6-deficient mice." (PMID 30232332, 2018). "In the context of infection, inflammasome-associated IL-1β shifts IL-6-dependent synthesis of APP to those involved in pathogen defense, including hepcidin, C-reactive protein, serum amyloid P, and serum amyloid A49." (PMID 29891920, 2018). "Further, treatment of infected WT or KO mice with anti-IL-6 neutralizing antibodies caused a reduction in weight loss during infection and also restored NK cells to WT levels in the KO mice [43•]." (PMID 30662816, 2018). "Interleukin-6 plays an important role in the acute-phase response that is rapidly induced by inflammation associated with infection, injury and other factors." (PMID 29910316, 2018). "Despite the low frequency of neurological complications associated with hRSV-infection, the cases reported exhibit similar profiles, which considers elevated levels of IL-6 in CSF." (PMID 30416428, 2018). "The area under the curve from receiver operating curve (ROC) analysis for the risk to develop a secondary acquired infection were all significantly > 0.8 for these four significant parameters (mHLA-DR at day 3–5, and IL-6, IL-8 and TNF-ɑ at day 1–2)." (PMID 29536210, 2018). "Infection of mice with L. monocytogenes causes strong induction of IL-6 which is required for effective bacteria control." (PMID 30169526, 2018). "Given the various roles of IL-6 in the immune system, concerns had been raised about a possible increase in the rate of serious infection associated with an IL-6 blocking strategy." (PMID 30423923, 2018). "We demonstrate here that the accumulation of macrophage and monocyte at the GI wall is associated with increased inflammatory cytokines IL-1β, IL-6, TNFα and INFγ-cytokines which signal recruitment of more inflammatory cells to sites of infection." (PMID 30249047, 2018). "We have examined prospective associations between exposure to common and serious infections during childhood and subsequent serum levels of IL-6, CRP and general intelligence." (PMID 29198208, 2018). "IL-6 and IL-17A were the primary cytokines positively and significantly associated with mortality at time point 1 (2–4 days after infection) (HR 1.72, 95% CI 1.25–2.37, p = 0.001) and (HR 2.36, 95% CI 1.35–4.15, p = 0.003), respectively." (PMID 29695270, 2018).
infection (continued). "Adoptive transfer of DCs loaded with Giardia antigens led to reduced infection intensity in both wild-type (WT)- and IL-6-deficient mice." (PMID 28979269, 2017). "More markedly, infection of IL-6 deficient mice with a similar, sub-lethal dose of H1N1 PR8 to the one used in this study results in a reduced proliferation of anti-viral T cells, and their failure to accumulate in sufficient numbers." (PMID 28953978, 2017). "Interleukin 6 (IL-6) is a pleiotropic cytokine implicated in inflammation, infection responses, hematopoiesis, and malignant diseases." (PMID 28938626, 2017). "Consistently, significantly higher concentrations of Th17-associated cytokines (including IL-17A and IL-6) were seen in lung homogenates from IRAK-M KO mice after smoke-induced exacerbations of LPS infection." (PMID 28951634, 2017). "Pro-inflammatory cytokines, including IFN-γ, TNF-α, IL-6, and IL-1β, are actively produced during the immune response to fight against pathogenic infection." (PMID 28454116, 2017). "In healthy individuals, the increased killing was associated with elevated production of IFN-γ, TNF-α and IL-6 in the presence of anti-IL-10 mAb only 6 hours after infection (p < 0.05, <0.001, <0.01 respectively)." (PMID 28216665, 2017). "TNF, IL-1β and IL-6 are cytokines referred to as pyrogenic and pro-inflammatory cytokines which predominate during infection and inflammation, associated with chronic inflammatory diseases." (PMID 28642550, 2017). "Inhibition of the antimicrobial actions of IFN-γ, TNF-α and IL-6 are likely to increase the susceptibility of the host to infection." (PMID 28216665, 2017). "In the early stages of infection, IL-6 was the key driver of virus-induced weight loss in WT and Ifitm3–/– mice and impinged on cellular antiviral immunity." (PMID 28240600, 2017). "IL-17R-, IL-23-, and IL-6-deficient mice rapidly succumbed to the infection at 22–25 d.p.i. compared to mice of the control group." (PMID 29033934, 2017). "IAV-induced MMP-9, TNF, and IL-6 in lungs of MALT1-deficient mice are significantly lower than in wild-type mice after intratracheal infection." (PMID 29018444, 2017). "The upregulation of IL-6 in our study immediately following infection, combined with the inverse correlation with DHAV-1, confirmed that IL-6 was associated with spontaneous resolution of DHAV-1 infection." (PMID 29201029, 2017). "Progression from early to late-stage infection was associated with significant increases in IL-6, IFN-γ, and IL-10 concentrations." (PMID 28927234, 2017). "Nevertheless, IL-6 knockout mice have similar morbidity and mortality rates to wild-type (WT) mice after infection with highly pathogenic H5N1 influenza virus." (PMID 28262742, 2017). "IL-6 production is promptly increased in acute inflammatory responses associated with infection, injury, trauma, and other stress." (PMID 28415707, 2017). "After infection with vesicular stomatitis virus or a chronic variant of lymphocytic choriomeningitis virus (LCMV) IL-6 promotes T-dependent antibody responses." (PMID 28953978, 2017). "In keeping with this recent publication, our analysis of intestinal tissue revealed no major differences in the plasma cell survival factors APRIL, BAFF, IL-6 or GM-CSF between eosinophil-deficient and control mice following infection." (PMID 27245920, 2016). "Adverse events associated with inhibition of IL-6 signaling include susceptibility to infection, cardiovascular toxicity, and gastrointestinal perforation." (PMID 26840088, 2016). "On the other hand, we detected a significant reduction in IL-6 concentration on the peritoneal exudates of genetically deficient mice after 5 days of infection." (PMID 27377650, 2016). "In 2 of 3 replicate experiments, RSV-A2 infection was also associated with significant increase in the apical release of IL-6 (p = 0.0003) and G-CSF (p = 0.006))." (PMID 26732674, 2016).
infection (continued). "Increased IL-6 levels have been previously reported in the Nlrx1−/− mice in other models associated with pathogen infection." (PMID 27105514, 2016). "The inflammatory response, particularly IL-6 production, varies greatly depending on the causative pathogen and the route of infection." (PMID 27834822, 2016). "We analysed the production of typical T-cell associated cytokines such as IL-6, IL-17 and IFNγ at the primary site of infection in the abscessed tissue of the thigh muscle." (PMID 27103319, 2016). "In response to an acute infection, trauma or exercise, acute elevations of IL-6 mediate anti-inflammatory effects, whereas chronic elevated levels of IL-6 are associated with pathogenic inflammation and with detrimental effects on metabolism." (PMID 27654305, 2016). "IL-6 has recently been implicated, however, as one of most pathogenic inflammatory cytokines, being associated with infection severity and complications in children who later died from AVL in Piaui State in northeastern Brazil." (PMID 27051668, 2016). "In this cohort of patients, the presence of anti-IL-6 AAbs were significantly associated with increased frequency of infections." (PMID 31557985, 2016). "As expected, IRF-5-deficient mice had a lower expression of IL-6 during the first week of infection." (PMID 26046638, 2015). "Here, Cl-CATH2 prominently blocked the genes of LPS–induced key pro-inflammatory cytokines (TNF-α, IL-6, and IL-1β) and iNOS, which can produce NO in a variety of tissues, and detectable in many cell types associated with infection and inflammation." (PMID 26194630, 2015). "As expected, TNFα, IL6 and IFNγ cytokines were enhanced by the infection, which have been associated with the progression of hepatic and cardiac injury." (PMID 25668433, 2015). "Increased concentrations of IL-6 in the cervical, amniotic, and vaginal fluid each reliably predict preterm birth associated with infection." (PMID 25961579, 2015). "AMs have been shown to produce IL-6 in response to in vitro infection with highly pathogenic influenza viruses." (PMID 25840995, 2015). "Hepcidin upregulation in the context of inflammation/infection is typically linked to signaling via the IL-6/STAT3 pathway." (PMID 26394303, 2015). "TNF, IL-1β and IL-6 pro-inflammatory cytokines play crucial roles in inflammation, infection, and responses to stress caused by different types of infections." (PMID 26657940, 2015). "TRIM30α knockdown or deficiency dramatically potentiated IFN-β and IL-6 production by infection with VSV in D2SC cells and BMDCs." (PMID 26114947, 2015). "TP4 treatment caused a decrease in TNF and IL-6 at the site of infection on days 1, 2 and 3, as compared with the MRSA infection group." (PMID 25955756, 2015). "Gender, two sites of infection (respiratory and urinary tracts) and plasma IL-6 were independently associated with mortality." (PMID 26649014, 2015). "Intranasal delivery of cationic PLGA nano/microparticles loaded with various FMDV DNA vaccine formulations encoding IL-6 as a molecular adjuvant enhanced protective immunity against infection by aerosolized FMDV." (PMID 26629822, 2015). "IL-6 is a cytokine, secreted by macrophages and T cells, thus displaying an important role in host defense and possibly during infections associated to antibiotic resistant microorganisms, such as Klebsiella pneumoniae and Enterococcus faecalis." (PMID 26223356, 2015). "IL-4 treatment reversed the infection-induced loss of staining for complex I and IV (P < 0.05), and IL-6 provided protection against loss of complex IV (P < 0.05)." (PMID 26481427, 2015). "Acute injuries, such as trauma, infection or surgery, cause the release of interleukin-6 and other cytokines that trigger the synthesis of CRP by the liver." (PMID 25159658, 2015).
infection (continued). "On univariate analysis for the BAL data, % neutrophils, IL-1β, IL-6, IL-8, IP-10, NTHi infection and respiratory viruses were inversely associated with NTHi-specific IFN-γ production by blood mononuclear cells." (PMID 26066058, 2015). "In our analysis of severe disease, IL-8 had the most robust predictive ability, although both eotaxin and IL-6 were also associated with more severe infection." (PMID 24643077, 2014). "On the other hand, IL6 is also secreted by macrophages and lymphocytes in response to injury or infection and has been associated with several pathological conditions as a marker of low-grade inflammation." (PMID 25136143, 2014). "Among others, proinflammatory cytokines such as interleukin-6 (IL-6) and -8 (IL-8) have been suggested as novel diagnostic markers, as they have shown an increase within a few hours after onset of infection in neonates." (PMID 25485809, 2014). "A similar susceptibility to infection is also seen in individuals with clinically relevant IL-6 autoantibodies." (PMID 24412616, 2014). "In response to infection caused by Legionella, macrophages produce inflammatory cytokines, such as interleukin 6 (IL-6), interleukin 1α (IL-1α), interleukin 1β (IL-1β), interleukin 12 (IL-12), interferon γ (INF γ), and tumor necrosis factor α (TNF-α)." (PMID 24821544, 2014). "After both 4 and 8 hours of infection, many of the up-regulated genes were those that encode pro-inflammatory cytokines (IL-1α, IL-1β, IL-6 and TNF-α) and chemokines (CCR7 and IL-8), all of which have been implicated in RA and CVD pathogenesis." (PMID 24874661, 2014). "In this respect the IL-6 and associated signaling cascades play a key role in controlling host defence and leukocyte trafficking during infection." (PMID 24410736, 2014). "For the i.n. infection, cytokine levels were very low locally at 1.5 hours but increased levels of IL-6, KC and IL-1β were found at 3 hours for susceptible mice (S/C-KO)." (PMID 24498223, 2014). "The Th17-associated cytokines IL-6, IL-23 and IL-17 were synthetized in higher levels in 1MT treated mice at 2 week after infection in both, resistant and susceptible mice." (PMID 25411790, 2014). "IL-6 is known to promote pulmonary inflammation and is a potential biomarker for patients at risk following infection with H1N1." (PMID 24809749, 2014). "Although IL-6-deficient mice showed lower steady-state Th17-cell levels, IL-6-independent Th17-cell responses occurred during in vivo infection." (PMID 24185641, 2014). "IL-6-deficient mice showed enhanced susceptibility during early infection with Mtb where T-cell mediated adaptive immunity is yet to fully develop." (PMID 24350246, 2013). "In fact, TNF-α and IL-6 have been shown to contribute to the leakiness of the BBB caused by the TLR-3 mediated infection of mice with WNV." (PMID 24236107, 2013). "During the early stage of infection, PPARγ deficiency significantly upregulated IL-6 and TNF-α expression in malnourished mice." (PMID 23469071, 2013). "In the NOD-like receptor signalling pathway (hsa04621) 10 genes (of a total of 57 pathway genes) were differentially expressed at 4 h post infection and five of them were upregulated more than 10-fold, encoding IL6, IL1B, BIRC3, CXCL1 and CXCL2." (PMID 23326599, 2013). "In contrast, greater IL-6 elevation was seen in the organs of infected TLR2-deficient animals during their survival period; at 3 d post-infection, the hepatic and blood IL-6 levels were 5.5- and 2.9-fold higher than those in infected WT mice, respectively." (PMID 24058538, 2013). "Other markers like serum interleukin-6 (IL-6) and interleukin-10 (IL-10) levels have been associated with more severe infection, multiple organ dysfunction and lethal outcome." (PMID 23374857, 2013). "Clarithromycin, by inhibiting the production of intracellular adhesion molecule ICAM-1 and secretion of IL-6 and IL-8, significantly influences the pathophysiological changes associated with infection caused by rhinovirus (RV)." (PMID 22969171, 2012).